FAM50B (family with sequence similarity 50 member B)
Synonyms: X5L; D6S2654E
Tractability: PROTAC: ubiquitination databases record sites on it.
Gene: Protein-coding gene on chromosome 6 (3,849,373 to 3,851,320, forward strand). Ensembl gene ENSG00000145945.
Subcellular location (Human Protein Atlas): Nucleoplasm; Cytokinetic bridge; Midbody
Gene Ontology:
Molecular function: protein binding
Biological process: chromatin organization
Cellular component: nucleus
Genetic constraint (gnomAD): Loss-of-function variants: 9 observed, 26.16 expected, observed/expected ratio (o/e) 0.34, 90% interval 0.21 to 0.6. The upper end of that interval is the gene's LOEUF score, 0.6, which puts it in group 2 of 6, group 1 being the genes least tolerant of losing a copy. Missense variants: 372 observed, 504.71 expected, observed/expected ratio (o/e) 0.74, 90% interval 0.68 to 0.8. Synonymous variants: 212 observed, 215.88 expected, observed/expected ratio (o/e) 0.98, 90% interval 0.88 to 1.1.
Homologues: Orthologues: macaque FAM50B (98% identical), rat Fam50b (85% identical), mouse Fam50b (84% identical), guinea pig FAM50B (79% identical), pig FAM50B (78% identical), zebrafish fam50a (73% identical), tropical clawed frog fam50a (70% identical), rabbit FAM50B (68% identical), Drosophila melanogaster CG12259 (58% identical), Caenorhabditis elegans C47E8.4 (43% identical). Paralogues in human: FAM50A (77% identical).
Diseases named in the same sentence as FAM50B in open-access papers:
FAM50B is named in the same sentence as 16 diseases in open-access papers, as found by Europe PMC text mining. Sharing a sentence is not in itself a finding about the gene and the disease. The quoted sentences say what the papers report.
asthenozoospermia (2 papers, 2019 to 2021). "FAM50B (family with sequence similarity 50, member B) was shown that average methylation level of FAM50B was lower in asthenozoospermia group than in control group." (PMID 31395792, 2019). "Some genes, such as FAM50B and GNAS, were reported to involve in the quality of sperm in asthenozoospermia through histone modification-type methylation." (PMID 34442404, 2021).
development delay (2 papers, 2019 to 2023). "Hypo-methylation of the same region of FAM50B has been previously reported in a patient with development delay, and has been associated with multi-locus imprinting defect (MLID)." (PMID 36071330, 2023). "DNA methylation changes of FAM50B in individuals with developmental delay/intellectual disability were observed." (PMID 31395792, 2019).
Intellectual disability (2 papers, 2019 to 2023). "Aberrant DNA methylation at PPIEL and FAM50B have been associated with bipolar disorder, and intellectual disability, respectively." (PMID 37594968, 2023).
adolescent idiopathic scoliosis (1 paper, 2021). A scoliosis with no known cause arising in adolescent. "Moreover, the two genes FAM50B and NAGPA are associated with adolescent idiopathic scoliosis (GeneCards®), which is a common feature in MFS patients." (PMID 34895303, 2021).
colon cancer (1 paper, 2021). "Interestingly, we observed FAM50B expression to be lost in tumours across a wide range of histological types including melanoma, bladder and colon cancer whereas it was ubiquitously expressed in normal tissue." (PMID 33637726, 2021).
glioblastoma (1 paper, 2022). The most malignant astrocytic tumor (WHO grade IV). "It has been validated that as a splicing factor, FAM50B serves an independent prognostic factor in glioblastoma." (PMID 35923577, 2022).
cancer (5 papers, 2021 to 2022). A tumor composed of atypical neoplastic, often pleomorphic cells that invade other tissues. "Loss of FAM50B (also known as Family with sequence similarity 50, member B) expression has also been identified in almost 4% of cancers in the TCGA database." (PMID 35923577, 2022). "FAM50A/FAM50B are particularly notable among our collection of genetic interactions because ~4% of cancers profiled by the TCGA show loss of FAM50B expression (0–10% across tumour categories), thus highlighting the FAM50A/FAM50B axis as a potential therapeutic target." (PMID 33637726, 2021). "The immunohistochemical staining of few CCD proteins in healthy and cancer tissues confirmed the potential gene candidates involved in tumorigenesis, such as Family With Sequence Similarity 50 Member B (FAM50B) gene or CD2 Cytoplasmic Tail Binding Protein 2 (CD2BP2)." (PMID 34112757, 2021). "Our studies reveal the fitness effects of FAM50A/FAM50B in cancer cells." (PMID 33637726, 2021). "Furthermore, a subsequent analysis on the possible role of the altered genes in CRC and IPD data sets in the survival of cancer patients (TCGA-COAD data sets) pointed to a significant influence on survival for eight of these genes (TUBB6, PAK6, SULT1A1, SLC11A1, TRAP1, FAM50B, SPON2, FES)." (PMID 34885088, 2021).
tumour (3 papers, 2019 to 2025). "The significant upregulation of MX2 in high-risk patients, along with the reduced expression of FAM50B, FUCA1, AKAP6, and FCER1A in this group, further supports their potential roles in tumour progression and immune regulation." (PMID 40329678, 2025). "Silencing of FAM50B occurs across a range of tumour types and in this context disruption of FAM50A reduces cellular fitness whilst promoting micronucleus formation and extensive perturbation of transcriptional programmes." (PMID 33637726, 2021). "Of note, using TCGA expression data and referencing our collection of 27 recurrent SL gene pairs, we determined that FAM50B was silenced in a significant proportion of tumours across a range of histologies; 0–10% in each tumour type examined." (PMID 33637726, 2021). "To ensure the EPIC array data truly reflects the methylation profile at imprinted DMRs, we performed pyrosequencing for the H19, KCNQ1OT1, and FAM50B regions which confirmed that the tumour sample is 22–24% less methylated than the corresponding placenta." (PMID 31357948, 2019).
FAM50B also shares sentences with these, for which no sentence is quoted: bipolar disorder (1 paper); Infertility (1); lung carcinoma (1); male infertility (1); melanoma (1); Parkinson disease (1); prostate carcinoma (1); respiratory diseases (1).